TNF (tumor necrosis factor)
Diseases named in the same sentence as TNF in open-access papers (continued):
Sharing a sentence is not in itself a finding about the gene and the disease.
sarcopenia (continued). "A series of in vitro and in vivo experiments have demonstrated that proinflammatory cytokines, including interleukins 1 and 6 and tumor necrosis factor, are deeply involved in the pathogenesis of sarcopenia via a mediator of the anorexia and proteolysis of skeletal muscle." (PMID 35566740, 2022). "In agreement with our results, a meta-analysis found that levels of CRP but not Interleukin 6 or tumor necrosis factor α were associated with sarcopenia." (PMID 35719155, 2022). "In addition, the sensitivity and specificity of the serum level of TNF-α for predicting sarcopenia were 74.42 and 47.3%, respectively [the cutoff point was 2.637 ng/ml, and the AUC value was 0.621 (95% CI: 0.511–0.731)]." (PMID 35903456, 2022). "In conclusion, elevated levels of TNF-α are significantly associated with the risk of sarcopenia, while variations perceived in circulating CRP can be explained by changes in the muscle mass indices only among individuals with sarcopenia." (PMID 36291982, 2022). "Higher IL-6, IL-17A, and TNF-α levels were observed in participants with sarcopenia (P < 0.05)." (PMID 35237317, 2022). "The VIP results indicated that TNF-α contributed the most to sarcopenia classification." (PMID 36160136, 2022). "However, we have clearly shown an increased plasma level of TNF-α in individuals with sarcopenia with a clear separation compared to a healthy control using PLS-DA plus logistic regression analysis." (PMID 36160136, 2022). "Furthermore, diet and nutrition play an important role in the onset of sarcopenia; for example, saturated fat can activate the innate immune system, leading to pro-inflammatory molecule production (IL6 and TNF-α), which, over time, causes insulin resistance." (PMID 35954203, 2022). "Logistic regression analysis was carried out to associate the inflammatory markers IL-6, TNF-α, and CRP with sarcopenia, and it was found that TNF-α was the only significant predictor of sarcopenia in tertile 3 or at levels > 71.2 [(OR = 5.85), 95% (1.07–32.08)]." (PMID 36291982, 2022). "There were substantial reductions in the levels of inflammation indicators such as CRP (from 6.17 μg/mL to 2.97 μg/mL) and TNF-α (from 10.24 pg/mL to 9.52 pg/mL), and this was especially pronounced in the sarcopenia group (CRP: from 6.32 μg/mL to 2.69 μg/mL; TNF-α: from 10.69 pg/mL to 9.35 pg/mL)." (PMID 33882026, 2021). "Compared with the HF group, the expression of IL-6 (P < 0.05) and TNF-α (P < 0.0001) in the HF + levosimendan group was significantly decreased, and the inflammation level of the HF + sarcopenia group was effectively improved after injection of levosimendan (P < 0.0001)." (PMID 35126176, 2021). "Third, sarcopenia is similar to a subclinical state of inflammation, wherein increased levels of circulating pro-inflammatory cytokines, such as IL-6 and TNFα, might potentiate pain sensitivity of the musculoskeletal system." (PMID 34026779, 2021). "The role of TNFα in the process of sarcopenia is yet to be fully understood." (PMID 33808526, 2021). "Furthermore, it has been shown that inflammatory cytokines, such as TNF-α, play an important role in muscle wasting in sarcopenia." (PMID 33804803, 2021). "Moreover, in the same muscle sarcopenia model, when TNF-α is administered to mice, muscle regeneration and muscle mass are weakened." (PMID 33804803, 2021). "Finally, sarcopenia is associated with inflammation demonstrated by increased serum C-reactive protein (CRP) levels, interleukin-6 (IL-6), and TNFα." (PMID 35010928, 2021). "Male sex (odds ratio (OR) 140.65), low body mass index (BMI) (OR 0.41), and use of tumor necrosis factor (TNF) inhibitors (OR 4.84) were associated with a low muscle mass as defined by the EWGS, while male sex, old age, and low BMI were associated with sarcopenia as defined by the AWGS." (PMID 34441751, 2021). "Similar to IL-6, TNFα appears crucial in cancer-related sarcopenia." (PMID 33804536, 2021).
sarcopenia (continued). "Among the many features of sarcopenia, increases in pro-inflammatory cytokines, such as IL-6 and TNF-α, may be responsible for the poor prognosis of patients with sarcopenia and endometrial cancer." (PMID 34928453, 2021). "Additionally, chronic inflammation has been also considered to be involved in the development of sarcopenia, due to the production of numerous pro-inflammatory cytokines, such as TNF and IL-6, which promote muscle catabolism." (PMID 34680417, 2021). "There are many common risk factors between sarcopenia and osteoporosis in COPD, including systemic inflammation (such as enhanced tumor necrosis factor (TNF)-α and IL-6), cigarette smoking, hypoxemia and/or hypercapnia, malnutrition, oxidative stress and reduced level of physical activity." (PMID 34650518, 2021). "In muscle, pro-inflammatory cytokines such as TNF regulate sarcopenia through the activation of the nuclear factor kappa B (NF-κB) transcription factor which, in turn, may activate the ubiquitin-proteasome system." (PMID 33023202, 2020). "Results from a cohort study in Chinese sarcopenia patients showed that high levels of the inflammatory cytokines TWEAK and TNF-α were associated with an increased risk of sarcopenia, while the insulin growth factor 1, insulin, and adiponectin were associated with a decreased risk of sarcopenia." (PMID 32054503, 2020). "In particular, elevated serum levels of IL-6 and TNF are markers of functional frailty and predictors of poor prognosis in the elderly, and increased levels of cellular IL-6 production are a significant predictor of sarcopenia." (PMID 33023202, 2020). "We investigated whether pharmacological blockade of TNFα by a well-established agent (Etanercept) might affect sarcopenia in aging mice." (PMID 33260150, 2020). "Sarcopenia is accompanied by muscle fat accumulation and an increase in pro-inflammatory cytokines, such as interleukin-6 (IL-6) and tissue necrosis factor alpha (TNF-α) within myocytes, which contribute to subsequent decreases in muscle mass and strength." (PMID 33222694, 2020). "The average levels of the four proinflammatory cytokines, including IL-1β, IL-6, IL-15, and TNF-α, were significantly increased in sarcopenia patients compared to those in young/healthy volunteers, while the concentrations of two other cytokines, IL-4 and IL-13, were not changed." (PMID 32226296, 2020). "In this sense, the release of IL-6 and TNF-α and its increase in serum would indicate a general pro-inflammatory state that could be active throughout the aging process, favoring the onset of sarcopenia." (PMID 33266508, 2020). "Thus, an increased plasma concentration of TNF-α correlates with lower muscle mass and strength, contributing to sarcopenia onset." (PMID 33266508, 2020). "High levels of circulating pro-inflammatory cytokines, such as CRP, tumor necrosis factor alpha (TNF-α), and IL-6 were shown to promote sarcopenia, a syndrome related with frailty and characterized by muscle breakdown and increased risk of muscle mass and strength loss." (PMID 31450694, 2019). "TNF‐α may contribute to sarcopenia by regulating the number or regenerative capacity of satellite cells." (PMID 30256507, 2018). "Furthermore, our findings show that TNF‐α expressed by myeloid cells contributes significantly to sarcopenia and is sufficient to maintain satellite cell numbers in aging, TNF‐α‐null mice." (PMID 30256507, 2018). "The increased nucleation of muscle fibers in old, TNF‐α‐null mice and the slowing of sarcopenia suggest that the two outcomes may be mechanistically related, although our in vivo data cannot definitively address the question." (PMID 30256507, 2018). "In this study, we used a mouse model with systemic genetic ablation of TNF‐α (TNF‐α‐null mice) to test the hypothesis that TNF‐α regulates sarcopenia and satellite cell function." (PMID 30256507, 2018).
sarcopenia (continued). "Because satellite cell senescence during aging can contribute to sarcopenia, we tested whether TNF‐α affects satellite cell activation in aging muscle." (PMID 30256507, 2018). "Moreover, in aging muscles, the development of sarcopenia is related to increased levels of the proinflammatory cytokines, i.e. tumor necrosis factor α and interleukin 6, and the development of mitochondrial dysfunction." (PMID 25695027, 2014). "In this sense, other hypotheses regarding sarcopenia pathophysiology focus on the role of chronic low-grade inflammation, specifically that related to circulating levels of IL-6 and tumor necrosis factor-α (TNF-α)." (PMID 25566189, 2014). "It is noteworthy that IL-6, TNF-α, CRP, and SAA have all been implicated in the pathogenesis of muscle atrophy in the context of sarcopenia or other muscle-wasting disorders." (PMID 25221511, 2014). "TNF-α has special effects that may contribute directly to sarcopenia, including increased basal energy expenditure, anorexia, loss of muscle and bone mass 'in vivo' and association with wasting/cachexia in chronic inflammatory disorders." (PMID 15904534, 2005). "The factors such as oxidative stress (H2O2), phosphosphingolipids (ceramide or palmitic acid), inflammatory cytokines (TNF-α), and dexamethasone have been directly applied to the myotubes to understand the molecular mechanisms involved in the development and the intervention of sarcopenia." (PMID 40623060, 2025). "However, it is yet to be clarified whether TNFα contributes to sarcopenia by inducing myofibers death through different types of programmed cell death and what is the original source of a local increase in TNFα level." (PMID 41345186, 2025). "Indeed, while IL-6 release in response to exercise appears to promote muscle anabolism and reduce circulating TNF-α levels, in the context of sarcopenia, a chronic low-grade inflammatory environment is established in which IL-6 exerts pro-inflammatory effects and promotes muscle catabolism." (PMID 40564069, 2025). "Furthermore, the study did not include circulating biomarkers commonly implicated in sarcopenia and cardiac cachexia, such as TNF-α, IL-6, or myostatin." (PMID 40566033, 2025). "Additionally, KEGG enrichment analysis indicated that this TCM formula may reduce sarcopenia via pathways including cancer signaling, TNF signaling, and PI3K-Akt pathways." (PMID 40259353, 2025). "Muscle‐derived myeloid might be the increased source of TNF‐α in sarcopenia." (PMID 39764565, 2025). "Aging-related sarcopenia is driven in part by chronic low grade systemic inflammation that has been named "inflamm-aging", and that is characterized by elevated pro-inflammatory cytokines such as TNF-α and IL‐6, which contribute to muscle catabolism and mitochondrial dysfunction." (PMID 40821925, 2025). "In sarcopenic patients, serum levels of irisin and TNF-α were significantly lower and higher than those noted in non-sarcopenic individuals, respectively, and these markers could be independent predictors of sarcopenia." (PMID 38672282, 2024). "The disruption of the normal muscle physiology, as in the case of sarcopenia, has been shown to lead to abnormal myokine signaling culminating in a proinflammatory environment characterized by impaired IL-6 signaling, increased TNF-alpha production and decreased IL-1ra and IL-10 levels." (PMID 38698153, 2024). "Moreover, recent years have seen the emergence of “TNF-α,” “insulin resistance”, “mitochondrial autophagy”, “signal pathways”, and “mechanisms” as focal points in the realm of OS in sarcopenia, encompassing related fundamental research and clinical translation." (PMID 39588187, 2024). "Inflammatory biomarkers such as C-reactive protein (CRP), granulocyte–monocyte colony-stimulating factor (GM-CSF), interferon-γ (IFNγ), interleukins (IL-6 and IL-8), myeloperoxidase (MPO), P-selectin, and tumor necrosis factor-α (TNF-α) may naturally be elevated in cases of acute sarcopenia." (PMID 39458423, 2024).
sarcopenia (continued). "Similarly, applying cut-offs for total protein and SMM, TNFα was the only biomarker found to be significantly associated with protein status, sarcopenia and with the presence or absence of sarcopenia." (PMID 37906352, 2023). "Thus, both skeletal muscle and cognitive functions are affected by chronic inflammation in vivo, and elevated levels of pro-inflammatory cytokines (IL-6 and TNF-α) and decreased levels of anti-inflammatory cytokines (IL-10) may contribute to sarcopenia and CI." (PMID 37962457, 2023). "In addition, sarcopenia could also result in the impairment of certain protein hydrolysis systems, such as the tumor necrosis factor (TNF)-α system, thereby facilitating the process of tumor migration and invasion." (PMID 37794517, 2023). "However, it is still unclear whether TNF-α contributes to sarcopenia by mediating pyroptosis, one type of PCD." (PMID 36823174, 2023). "However, it is unclear whether TNF-α contributes to sarcopenia by inducing myofibers death through the interconnection of different types of PCD, such as the crosstalk between apoptosis and pyroptosis." (PMID 36823174, 2023). "However, when stratified according to sarcopenia status, IL-6 was positively correlated with UGT among the sarcopenia group (r = 0.48, p-value < 0.05), and negatively correlated with TNF-α among the control group, respectively (r = −0.40, r = −0.45, p-value < 0.01)." (PMID 36291982, 2022). "Regarding the mixed results observed in our study, CRP, but not IL-10 and TNF-α, significantly related to low physical performance, a systematic review and meta-analysis of 17 studies with 11,249 individuals also showed that only CRP, but not TNF-α and IL-6, is associated with sarcopenia." (PMID 35525916, 2022). "Therefore, the present study explores the relationship between sarcopenia and IL-4, IL-6, IL-10, and TNF-α in the elderly population of agricultural and pastoral areas of Xinjiang, China, and is expected to lay a preliminary foundation for understanding its underlying mechanism." (PMID 36160136, 2022). "Previously, we demonstrated that TNFα-expressing myeloid lineage cells, including macrophages and granulocytes, accumulate in skeletal muscles in mice during aging, which contributes to sarcopenia, suggesting denervation-induced TNFα may also come from myeloid cells." (PMID 36618945, 2022). "Therefore, if we apply bDMARDS, which antagonizes TNF-α and IL-6, to inhibit inflammatory cytokine-induced proteolytic metabolism in a timely manner at an early stage of the disease, we can prevent the development of sarcopenia and OP." (PMID 35676311, 2022). "Moreover, TNFα, through the activation of nuclear factor-kB (NFkB), perpetuates hepatic inflammation, in a vicious circle that amplifies the inflammatory milieu in both sarcopenia and NAFLD." (PMID 35052859, 2022). "Moreover, cross sectional studies have suggested the increase of IL-6 and TNF-a in sarcopenia." (PMID 34493690, 2021). "In addition, both IS and LPS induce inflammatory cytokine expression (IL-6 and TNF-α) which in turn may sustain sarcopenia." (PMID 33804536, 2021). "Although the role of the ubiquitin–proteasome pathway in sarcopenia is less clear, a recent review suggested that elevated levels of pro-inflammatory mediators including TNFα might upregulate this proteolytic pathway by regulating the ubiquitin–proteasome system." (PMID 34576187, 2021). "An incremental clinical benefit of blocking the catabolic effects on skeletal muscle tissue could be observed in IBD patients with sarcopenia treated by biologics including anti-TNF alpha agents and newer anti-interleukin, anti-integrin, and JAK inhibitors agents used for treatment of IBD." (PMID 34326845, 2021). "Additionally, in CD, sarcopenia is associated with primary non-response to anti-TNF treatment, and therefore sarcopenic IBD patients need adjusted dosing." (PMID 32784808, 2020).
sarcopenia (continued). "Furthermore, GJG has also been reported to suppress sarcopenia via the insulin growth factor-1/insulin pathway, maintains the expression of mitochondrial-related transcription factors, and suppresses the expression of TNF-α." (PMID 32766269, 2020). "Recent studies show that sarcopenia is associated with low-grade systemic inflammation, as indicated by increased inflammatory cytokines (IL-1, IL-6, and TNFα) leading to oxidative stress, which together with mitochondrial dysfunction, could be central to the pathogenesis of sarcopenia." (PMID 31888500, 2019). "To date, TNF-α, IL-6, albumin and CRP have shown a relation with the development of low muscle strength or muscle mass over time, however, the current body of evidence fails to reveal a marker of chronic inflammation that is univocally associated with measures of sarcopenia in older people." (PMID 31455238, 2019). "Interestingly, TNF‐α is expressed in both myofibers and tissue‐resident macrophages in aging muscle, suggesting that TNF‐α might serve as one of the nodes integrating intrinsic and extrinsic factors affecting sarcopenia." (PMID 30256507, 2018). "This study aimed to evaluate the correlation between inflammatory biomarkers such as C-reactive protein (CRP), tumor necrosis factor-alpha (TNF-α), interleukin-6 (IL-6), and the anabolic hormone insulin-like growth factor-1 (IGF-1) with sarcopenia." (PMID 42267078, 2026). "This study confirmed the significant association between elevated inflammatory markers (including TNF‐α and CRP), and sarcopenia among patients with CKD." (PMID 41457350, 2026). "Further research suggests that sarcopenia in patients with COPD is strongly correlated with systemic inflammation; among inflammatory mediators, serum TNF‐α levels are a decisive factor in patients with COPD and sarcopenia." (PMID 41582634, 2026). "In patients with sarcopenia, CHI3L1 is upregulated and secreted by skeletal muscle via the TNF-α/TNFR1 signaling pathway, protecting myocytes from damage, while concurrently promoting HCC progression by inducing the accumulation of LPO products." (PMID 41568005, 2025). "Comparison of sarcopenia related factors between low and high groups based on myostatin, P3NP and TNF‐α cutoff values." (PMID 40162588, 2025). "It is also known that a chronic inflammatory milieu (high IL-6, TNF-α, interleukin-1 (IL-1), and C-reactive protein “CRP”) is correlated with sarcopenia in aging." (PMID 41348866, 2025). "From the results, the network pharmacology analysis revealed the key mediating roles of IL-6 and TNF-α in the regulatory network of ECG, testosterone, and sarcopenia." (PMID 40724319, 2025). "Inflammatory cytokines (e.g., TNF-α, IL-6) activate NF-κB and MAPK signaling pathways, exacerb muscle protein degradation and suppressing synthesis, thereby directly promoting sarcopenia." (PMID 41199827, 2025). "However, when mice with dexamethasone‐induced sarcopenia were treated with puerarin, the expression levels and phosphorylation states of these proteins were significantly decreased, indicating that puerarin can effectively inhibit the activation of the TNF‐α/NF‐κB signaling pathway." (PMID 40255543, 2025). "Growing evidence shows that serum levels of tumor necrosis factor (TNF)-α, interleukin (IL)-6, and C-reactive protein (CRP) are elevated in individuals with sarcopenia, typically reaching levels 2–4 times higher than those observed in younger controls." (PMID 40678078, 2025). "Elevated levels of inflammatory cytokines, such as tumor necrosis factor-alpha (TNF-α), interleukin-6 (IL-6), and C-reactive protein (CRP), have been consistently observed in older adults with sarcopenia." (PMID 40283772, 2025). "Of these, pro-inflammatory factors [tumor necrosis factor (TNF-α), interleukin (IL-1β), and interferon (IFN-γ)] can inhibit the expression of growth hormone and promote the occurrence of sarcopenia." (PMID 41164369, 2025).